VIM (vimentin)
Diseases named in the same sentence as VIM in open-access papers (continued):
Sharing a sentence is not in itself a finding about the gene and the disease.
tumor (continued). "(B) The levels of vimentin in 109 paired NSCLC tissues and adjacent normal non-tumor tissues." (PMID 31420013, 2019). "Further analysis showed no significant changes in the tumor microenvironment after 24 h of culturing as the level of vimentin and α-SMA, fibroblast markers remained unaltered (third and fourth panel lines)." (PMID 30723707, 2019). "Integrin α11 and vimentin also showed co-localization in the tumor stroma, but interestingly, α11 chain expression was also observed in stroma cells with no detectable expression of vimentin." (PMID 31159419, 2019). "Immunohistochemically, the tumor cells were strongly positive for vimentin, the staining was negative for myoglobin, desmin, or muscle type actin." (PMID 31022624, 2019). "RT-qPCR assays revealed that the expression of maspin affected the gene expressions of cyclin D1, p21, vimentin MMP2, and MMP9 in xenograft tumors, which suggested that maspin may modulate these genes to regulate tumor growth in vivo." (PMID 31861435, 2019). "The tumor cells were positive for cytokeratin, nuclear/membranous β-catenin, CD10, and CD56 and were negative for chromogranin A, synaptophysin, progesterone receptor, vimentin, and Bcl-10." (PMID 31784920, 2019). "Notably, tumor sections from fatostain-treated mice showed a significantly lower staining of SREPB1, ZEB1, and vimentin, while also showing increased E-cadherin, agreeing with the in vitro observations." (PMID 31861383, 2019). "Furthermore, during tumor cell EMT, E-cadherin expression (epithelial cell marker) was reduced, whereas N-cadherin and vimentin expression (mesenchymal cell markers)were increased induced." (PMID 31355138, 2019). "We also detected abundant αDG expression in vimentin+, EphA3+, GFAPlow MES-like tumour regions." (PMID 31463571, 2019). "In addition, we detected fibroblasts in 2D or 3D co-culture models and tumor tissues, found that α-SMA and vimentin protein expression was significantly increased, indicating that some cells transformed into CAFs." (PMID 31417646, 2019). "In a follow-up experiment, we found that upregulated PAX6 expression elevated the expression of EMT marker genes (N-cadherin, vimentin, FSP-1), stem cell biomarkers (CD44, CD133, ALCAM), and the proliferation marker Ki67, yet it inhibited E-cadherin in tumor tissues as assessed by IHC." (PMID 31024010, 2019). "Similarly, in tumor tissues from AOM/DSS-treated mice, KLF4 levels were negatively correlated with mesenchymal markers including SNAI2, β-catenin, and vimentin and positively correlated with the epithelial marker E-cadherin." (PMID 32566755, 2019). "CTCs detected in our different PDOX tumor models of TNBC expressed basic epithelial (CK+) and/or mesenchymal (VIM+) markers, suggesting that individual CTCs may be in the process of undergoing epithelial-mesenchymal transition (EMT)." (PMID 31462307, 2019). "In silico analysis confirmed that the expression of CXCR4 in the primary tumor significantly correlated not only with the expression of its ligand CXCL12 (Spearman's coefficient, rs = 0.4920) but also with the expression of VIM (rs = 0.4779) and CD163 (rs = 0.4853)." (PMID 29849822, 2018). "Also with respect to UCB, EMT is involved in tumor progression and metastasis and expression levels of FGFRs are correlated with expression levels of EMT marker such as E-cadherin and vimentin." (PMID 29731962, 2018). "As vimentin staining is not homogenous, we cannot exclude that vimentin is not expressed by activated pancreatic stellate cells within the tumor." (PMID 30065235, 2018). "The IHC analysis obtained from specimens derived from superior limb and parathyroid metastases of one patient whose tumor had progressed showed an increase of positive cells for HMGA1, E2F1, and vimentin supporting the role of HMGA1/E2F1 axis in MLS progression." (PMID 29980789, 2018).
tumor (continued). "On the other hand, the most characteristic feature of Mes-like tumor cells, tumor cell expression of VIM and ZEB211, is not traceable using whole biopsy mRNA expression as Mes-like tumors are infiltrated by stromal cells." (PMID 29487377, 2018). "The resected tumor was positive for GFAP, Ki67, vimentin, CD56, and nestin." (PMID 30583471, 2018). "Like the tumours in SCID/beige mice, these tumours also showed variable staining for VIMENTIN, DESMIN and SMA as well as an absence of staining for MYOD1 and MYOGENIN." (PMID 29731980, 2018). "Vimentin-positive cells were absent in the central tumour, and, within the bulk, positive cells were concentrated at the periphery." (PMID 29976164, 2018). "Immunohistochemical assay of tumor tissues revealed that PLC-PAR1 and HepG2/M/PAR1 overexpressing tumors exhibited high expression levels of VEGFR1, VEGFR2, VE-cadherin, and vimentin and a low expression level of E-cadherin while Twist1 silence reversed the regulation effects of PAR1." (PMID 30081924, 2018). "In repeated biopsy in July 2015 histopathological workup showed a pleomorphic epitheloid tumor with small to medium sized cells expressing vimentin and melan-A while being negative for cytokeratin establishing the diagnosis of PEComa of the liver." (PMID 29463266, 2018). "Like the results of IHC and western blotting, the RT-PCR results found that decreased expression of E-cadherin and increased expression of vimentin and N-cadherin in CLCA4-silenced cells compared with the control tumor cells, while opposite expression was observed in CLCA4-transfected cells." (PMID 30312171, 2018). "To test whether the tumor-promoting effects of MMSET are mediated by Twist1 in EC, we examined the protein expression of Twist1 and its downstream effectors Vimentin and E-cadherin in EC cells following either MMSET overexpression or knockdown." (PMID 29796186, 2018). "Vimentin mRNA was abundant in the tumour cells of each model (data not shown), but was not differentially expressed." (PMID 29720474, 2018). "On immunohistochemistry, the tumor cells expressed vimentin and melan-A, but were negative for cytokeratin." (PMID 29463266, 2018). "Accordingly, K-Ras/NICD tumors displayed a high desmoplastic reaction, as revealed by histologic analysis and highlighted by immunoreactivity for vimentin (VIM) in the stromal fibroblasts and myofibroblasts as well as strong Sirius Red staining of the collagen fibers within the tumor tissue." (PMID 29348467, 2018). "In addition, Zeb1 knock-out in orthotopic mouse xenograft models significantly affected the tumor growth and EMT by switching the expression of Vimentin and E-cadherin." (PMID 30158928, 2018). "Also, Silibinin, a compound that has been shown to suppress vimentin expression, reverse EMT and inhibit tumour–stromal communication, also inhibits cancer." (PMID 30248895, 2018). "Likewise, the tumours produced by injecting HCC-shTGM2 cells alone were significantly lighter and showed increased E-cadherin expression and reduced vimentin expression compared with injections of HCC-Mock’ cells alone." (PMID 30393774, 2018). "These fibroblast cultures derived from tumor tissues expressed Vimentin and harbored no KRAS mutation as did the patient’s tumor, distinguishing them from epithelial tumor cells." (PMID 29587663, 2018). "The decrease in E‐Cadherin expression in clone 5 cells and an absence of Vimentin in all investigated HepG2 tumours (in vivo data for Vimentin not shown) were additionally verified in vitro by Western Blot." (PMID 30280520, 2018). "Additionally, IHC for serial slices of human tumor HCC tissue demonstrated that Rnd1 expression is positively correlated with E-cadherin (R = 0.563, P = 0.010) and negatively correlated with vimentin expression (R = −0.567, P = 0.009)." (PMID 29706627, 2018).
tumor (continued). "In CSCCs, tumor cells with COL7A1 knockdown manifested increased migration and higher invasiveness, accompanied by the alteration of EMT marker expression (the decreased expression of E-cadherin and the increased expression of MMP2 and vimentin)." (PMID 29499655, 2018). "The tumours arising from injected HCC-TGM2 OE cells (vs. inoculated HCC-Mock cells) had a greater mass, accompanied by reduced E-cadherin expression and increased vimentin expression." (PMID 30393774, 2018). "These tumours similarly showed an absence of staining for all of the markers that were used to characterise the tumours in 129Sv mice, except VIMENTIN." (PMID 29731980, 2018). "We studied a retrospective cohort of 160 consecutive surgically treated NSCLC patients with available frozen tumor samples for expression of EMT markers (CDH1, CTNNB1, CDH2, and VIMENTIN), inducers (TGFB1, c‐MET, and CAIX), and transcription factors (EMT‐TF:SNAI1, SNAI2, ZEB1, TWIST1, and TWIST2)." (PMID 29845746, 2018). "Moreover, cells expressing the mesenchymal marker, vimentin, and cells expressing CK8 were mutually exclusive in most of these tumor cells." (PMID 29329590, 2018). "Expression of cell proliferation index (Ki-67) and EMT biomarkers of E-cadherin/Vimentin, which was detected by qRT-PCR and IHC, indicated that Neferine treatment significantly depressed HCC EMT phenotype and cell proliferation in xenograft tumor." (PMID 28134289, 2017). "Mangiferin considerably decreased tumor proliferation, weight, and volume, and enhanced apoptosis, as well as also decreased the expression levels of MMP-7, MMP-9, active β-catenin, vimentin, while increasing the expression of E-cadherin in in vitro MDA-MB-231 xenograft mice." (PMID 28464819, 2017). "Xenografted tumours arose from the injection of MCF7 cells alone showed positivity for class I HLA, thus confirming human origin, negativity for CD31, positivity for VEGF and cytokeratin, and negativity for vimentin." (PMID 28102844, 2017). "Further characterization of EMT markers revealed that E-Cadherin staining was positive, whereas Vimentin and alpha-smooth muscle actin (aSMA) were negative within the tumor." (PMID 28855609, 2017). "According to our results, wogonoside could suppress tumor metastasis through inhibition of primary tumor invasion by increasing the expression of E-cadherin and decreasing the expression of MMP-9, vimentin and Twist1." (PMID 28774312, 2017). "Vimentin was diffusely present in both spindle and epithelial components, whereas epithelial cells expressed cytokeratin (AE1/AE3) relatively higher than spindle tumour cells." (PMID 28511645, 2017). "Therefore, Vimentin appears to be a general target during GSK-3β inhibition, implying that GSK-3β participates in the protection of mesenchymal characteristics in tumor cells." (PMID 28821798, 2017). "Recently, we investigated the effects of NP surface-modification with cell-penetrating peptides (CPPs), stealth ligands, and tumor targeting ligands (MPG (unabbreviated notation), PEG, and Vimentin, respectively), on NP penetration and distribution within the hypo-vascularized tumor environment." (PMID 28982361, 2017). "Since VIM has been involved in attachment, migration, and cell signaling, our results justified additional studies to validate the functional role of GFAP−/VIM+ tumor cells in PXA (and other PLGGs) recurrence." (PMID 29152094, 2017). "In support of the point that epithelial-mesenchymal transition (EMT) is closely associated with metastasis of tumor cells, we found that in small LoVo cells not large cells, knockdown of YAP1 down-regulated the expression of vimentin, a key EMT protein." (PMID 29296212, 2017).
tumor (continued). "Furthermore, we stained the intracranial tumours with IKBKE, YAP1, MMP-2, MMP-9, E-cadherin, N-cadherin, β-catenin, vimentin, and snail." (PMID 28548934, 2017). "These signaling events eventually increase the expression of a group of genes such as N-cadherin, vimentin and Zeb1, which trigger metastatic changes including epithelial mesenchymal transition (EMT), enhancement of motility and the invasiveness of tumor cells." (PMID 29133945, 2017). "Immunohistochemically, the tumor cells showed strong cytoplasmic expression for CK7, S-100, vimentin, EMA, nuclear expression for SOX10, focal membranous for CA9, and were negative for thyroglobulin, actin, calponin, PAX8, CD10, CK20, CDX2, CD117, DOG-1 and SMA." (PMID 29041930, 2017). "These cells were identified as tumor cells by positive staining for pan-cytokeratin and absence of staining for vimentin." (PMID 28389503, 2017). "Immunofluorescence staining of the sectioned tumours revealed patterns of E-cadherin and vimentin protein expression which were not consistent with what had been observed in in vitro cultured cells." (PMID 28094783, 2017). "Several studies on multiple tumor types demonstrated that vimentin is specifically expressed in invasive cell lines, but not in stationary cancer cells." (PMID 28096473, 2017). "The alteration in the expression of N-cadherin in tumor after cordycepin treatment has similar, but less extent, trend to vimentin (data not shown)." (PMID 28406456, 2017). "The results revealed that the expression levels of HMGB1, α-SMA, vimentin, and β-catenin were significantly increased in tumour tissue when compared with adjacent non-tumour tissue." (PMID 28727734, 2017). "Knockdown of BMPRIA in vivo delayed tumour onset, and also subsequent growth of tumours and improved survival, despite conversely seeming to induce EMT-like tumour transitions, such as increased Vimentin." (PMID 28733469, 2017). "WT MDA-MB-468 tumor cells that were found in the lung as micrometastases expressed E-cadherin, whereas no vimentin-positive cells were observed." (PMID 28750639, 2017). "Circulating tumor cells were defined based on positive staining for vimentin, negative staining for CD45, and nuclear morphology distinct from that of normal white blood cells." (PMID 29108279, 2017). "This was reflected by the correlation of PAR-1 gene expression with stroma markers like CD163, CD31 and vimentin, and ECM proteins like collagen and fibronectin, as well as by a significant increase in the intensity of PAR-1 staining in stromal cells of tumor tissue compared with normal lung tissue." (PMID 28173772, 2017). "In contrast, the primary tumour-derived cell lines, OPCT-1 and OPCT-2, exhibited differential non-focal expression of vimentin, with sophisticated networks of vimentin fibres throughout some cells and lower levels of vimentin appearing around the nucleus in other cells." (PMID 28094783, 2017). "Tumor cells showed strong positivity for CD34, vimentin and Bcl-2." (PMID 29075420, 2017). "The tumor cells showed positive of CD68, S100, Vimentin and Ki-67 index 80%." (PMID 28386111, 2017). "It is of note that, at the mRNA level, a large proportion of the basal/SCC‐like tumours in the same consensus cluster expressed VIM, but the protein was expressed in infiltrating mesenchymal cells and not by the tumour cells in these cases." (PMID 28195647, 2017). "Additionally, JPJD can upregulate the expression of E-cadherin and Smad2/3 in the cytoplasm and downregulate the expression of Vimentin, p-Smad2/3, and Snail in the orthotopic CRC tumor tissues." (PMID 28299321, 2017). "The reduced vimentin staining of RLN and DLN in the Foxy-5 treated animals confirmed the decreased BLI intensities observed in the lymph nodes in vivo, suggesting that Foxy-5 significantly reduces the number of tumor cells in the RLN and DLN." (PMID 28886116, 2017).
tumor (continued). "Vimentin concentration was highest in grade 3 tumours followed by grade 2 and 1 but that for DAPK1 was not significant." (PMID 28616237, 2017). "Immunohistochemistry (IHC) of vimentin differentiated between metastasized tumour cells (with staining) from normal adjacent cells (without staining)." (PMID 29069715, 2017). "Consistent with this, we demonstrate that supplementation with NC derived stromal cells promotes proliferation and tumor aggressiveness in vivo, increasing expression of mesenchymal genes such as CD44, S100A10, ENG, VIM and ACTA2 (SMA), being the last one a typical marker of CAFs." (PMID 29163787, 2017). "For the mechanism, we found Med19 could regulate the expression of multiple genes relevant to tumor growth and metastasis, including P27, pAKT, pPI3K, IGF1R, E-Cadherin, N-Cadherin, Vimentin, ZEB2, Snail-1 and Snail-2." (PMID 28125713, 2017). "The tumor cells showed generally positive for vimentin and negative for h-CALD, CD34, desmin, CD163, AE1/AE3, CK7 and CK20." (PMID 28320435, 2017). "Histological evaluation of the septated, cystic mass revealed tumour cells forming an irregular patternless pattern; immunohistochemically, the cells tested positive for vimentin, CD34, CD99 and STAT6 but negative for keratin (AE1-AE3), CD31 and S100." (PMID 28865431, 2017). "On immunohistochemistry tumor cells exhibit strong diffuse positivity with smooth muscle actin and vimentin, and are negative for cytokeratin, CD34 and S100." (PMID 29216875, 2017). "The expression levels of Snail, E-cadherin, N-cadherin and Vimentin were significantly different between the tumor adjacent normal and tumor tissues." (PMID 28570699, 2017). "Similarly to the other tumours generated in this study, these allograft tumours stained positively for PMEL, CATHEPSIN K, PDGFRβ, SMA and VIMENTIN, expressed PMEL by western blotting, and exhibited a similar frequency of PMEL expressing cells." (PMID 29133867, 2017). "Therefore, we used immunostaining to detect the expression levels of STC2, pAKT, Snail, vimentin, and E-cadherin in a tissue microarray containing tumor samples from 298 HNSCC patients, as well as tissue from 98 non-tumor controls." (PMID 27863406, 2017). "As expected, NB5t primary cells showed increased expression of mesenchymal genes (NT5E, ENG, ACTA2, MME, CD44, VIM or ALPL), while NB5t tumor sample expressed mostly neuronal genes (TH, ENO2, NCAM1, DDC or CHGB) reflecting the neuroblastic phenotype of stage 4/M NB tumors." (PMID 29163787, 2017). "Surprisingly, bioinformatics showed that miR-320a could target vimentin as well as directly bind USP14, which might contribute to the tumor suppressor role of miR-320a in GC." (PMID 27448976, 2017). "Significantly, tumor tissues derived from UMUC-3/shScr xenografts showed reduced expression of the epithelial marker E-cadherin and enhanced levels of the mesenchimal protein vimentin compared to UMUC-3/shPGRN orthotopic xenografts." (PMID 27220888, 2016). "Finally, knockdown of vimentin in HPSE expressing MM cells resulted in significantly attenuated MM cell dissemination and tumor growth in vivo." (PMID 26849235, 2016). "In addition, there was a decreased expression of mesenchymal markers such as N-Cadherin, P-Cadherin, Vimentin, SNAIL, SLUG, TWIST and SMA in HSP70-2 shRNA4 treated tumor compared to NC shRNA treated tumors." (PMID 27658496, 2016). "The CTC was defined as a cell with a large tumor-like nucleus that stained positive to cytokeratin and vimentin and negative to CD45." (PMID 27369977, 2016). "We next screened by flow cytometry this panel of cell tumour phenotypes with epithelial markers (EpCAM, E-cadherin, Muc1, claudin-3 andclaudin-4) or non-epithelial markers (N-cadherin, vimentin, CD66, EGFR, FGFR, EphB4,ALDH1 and CD49f)." (PMID 27711186, 2016).